SLC52A2 (solute carrier family 52 member 2)
Diseases named in the same sentence as SLC52A2 in open-access papers:
SLC52A2 is named in the same sentence as 47 diseases in open-access papers, as found by Europe PMC text mining. Sharing a sentence is not in itself a finding about the gene and the disease. The quoted sentences say what the papers report.
Brown-Vialetto-Van Laere syndrome (12 papers, 2014 to 2025). "Brown-Vialetto-Van Laere syndrome (BVVLS) is an extremely rare genetic neurological disorder caused by riboflavin transport deficiency, an autosomal recessive condition mostly associated with mutations in the SLC52A2 and SLC52A3 genes." (PMID 40539137, 2025). "Inborn mutations of SLC52A2 are associated with Brown-Vialetto-van Laere syndrome, a rare neurological disorder characterized by infancy onset." (PMID 31500345, 2019). "Brown-Vialetto-Van Laere syndrome is a rare disorder characterized by motor, sensory, and cranial neuronopathies, associated with mutations in SLC52A2 and SLC52A3 genes that code for human riboflavin transporters RFVT2 and RFVT3, respectively." (PMID 28856173, 2017). "Recessive mutations in the SLC52A3 gene can also result in Brown-Vialetto-Van Laere syndrome; however, there are differences in the phenotype of patients harbouring SLC52A2 mutations compared with the phenotype of patients with SLC52A3 mutations." (PMID 24253200, 2014). "RF transporter deficiency (RTD; also known as Brown-Vialetto-Van Laere syndrome) is a progressive inherited neuropathy with childhood onset, caused by mutations in SLC52A2 (RTD2) or SLC52A3 (RTD3), which encode the human RF transporters 2 (RFVT2) and 3 (RFVT3), respectively." (PMID 40684659, 2025). "Thus far, three separate subtypes of RTD2 are described—type 1, 2 and 3—but, previously, RTD was classified as two separate genetic defects: Brown–Vialetto–Van Laere syndrome and Fazio–Londe syndrome, caused by mutations in the SLC52A2 and SLC52A3 genes, respectively." (PMID 41295274, 2025). "In 2010, mutations SLC52A2 (encoding RFVT2) and SLC52A3 (encoding RFVT3) were shown to cause the neurodegenerative disorder Brown-Vialetto-Van Laere syndrome (BVVL) which, therefore, designated it as a riboflavin transporter deficiency (RTD)." (PMID 33036493, 2020). "Loss-of-function mutations in two riboflavin transporter genes, SLC52A2 and SLC52A3, have recently been linked to Brown-Vialetto-Van Laere syndrome." (PMID 29053833, 2017). "We recently reported the identification of SLC52A2, encoding riboflavin transporter RFVT2, as a new causative gene for Brown-Vialetto-Van Laere syndrome." (PMID 24253200, 2014). "Riboflavin transporter deficiency (RTD, OMIM 614707), formerly known as Brown‐Vialetto‐Van Laere (BVVL) or Fazio Londe syndrome (OMIM 211500) is an inborn error of metabolism caused by variants in SLC52A2 or SLC52A3, encoding the human riboflavin transporters RFVT2 and RFVT3, respectively." (PMID 38974615, 2024). "Brown-Vialetto-Van Laere Syndrome (BVVLS), a rare neurological disorder characterized by motor, sensory, and cranial neuronopathies, is mainly associated with defective riboflavin transporters encoded by SLC52A2 and SLC52A3 genes." (PMID 31064337, 2019). "Early onset weakness in the upper limbs and neck is almost invariably seen in patients with mutations in SLC52A2, in contrast to those patients with SLC52A3 mutations or genetically unclassified Brown-Vialetto-Van Laere syndrome, in whom the onset of weakness is often more generalized." (PMID 24253200, 2014). "Whole exome sequencing identified a known pathogenic mutation in the SLC52A2 gene consistent with a diagnosis of Brown-Vialetto-Van Laere syndrome despite the absence of common symptoms including motor neuropathy, bulbar palsy, optic atrophy, and sensorineural hearing loss." (PMID 30377535, 2018). "Another distinctive feature of patients with SLC52A2 mutations is a lack of upper motor neuron signs in the lower limbs, a commonly reported clinical feature of Brown-Vialetto-Van Laere syndrome and, in particular, reported in patients with mutations in SLC52A3." (PMID 24253200, 2014).
optic atrophy (4 papers, 2014 to 2020). A disorder characterized by loss of optic nerve fibers. "It was previously noted that the distinct phenotype of upper limb and axial weakness, hearing loss and optic atrophy could be attributed only to patients harbouring SLC52A2 mutations." (PMID 29053833, 2017).
Ataxia (2 papers, 2014 to 2025). Ataxia refers to impaired coordination of voluntary muscle movement. "This autosomal recessive disorder is caused by pathogenic mutations in the SLC52A2 gene leading to progressive ataxia, polyneuropathy, and hearing and visual impairment." (PMID 40710590, 2025).
gastric cancer (2 papers, 2016 to 2022). A primary or metastatic malignant neoplasm involving the stomach. "We verified the SLC52A2 expression in hepatocellular carcinoma, gastric cancer, colon cancer, and rectal cancer using immunohistochemistry." (PMID 34991609, 2022). "They found that, compared with matched adjacent noncancerous, SLC52A2 showed increased copy number in 44% gastric cancer tissues and its expression was upregulated in 56% gastric cancer tissues." (PMID 34991609, 2022).
ovarian carcinoma (2 papers, 2016 to 2022). A malignant neoplasm originating from the surface ovarian epithelium. "Also, they compared serum SLC52A2 levels in patients with advanced ovarian cancer and normal age-matched controls by enzyme-linked immunosorbent assay." (PMID 34991609, 2022). "Similarly, Vathipadiekal found the significant upregulation of SLC52A2 in ovarian cancer tissues by using public data (P < 0.001)." (PMID 34991609, 2022). "Interestingly, SLC52A2 also present in the list of genes, whose expression is associated with CNA alterations, has been previously proposed as a novel candidate blood-based marker for ovarian cancer." (PMID 27341628, 2016).
Viral infection (2 papers, 2009 to 2025). "SLC52A2 is expressed at extremely high levels in these cultured cells, so it is possible that viral infection occurs using SLC52A2 in these cell lines." (PMID 40574751, 2025). "Viral infection using the PERV-A and PERV-A/C Env-pseudotyped viruses was confirmed in MDTF-chSLC52A2, MDTF-huSLC52A2, MDTF-chSLC52A1, and MDTF-huSLC52A1 cells, thereby indicating that chimpanzee and human SLC52A2 and SLC52A1 expression confers susceptibility to infection with pseudo-typed PERV." (PMID 40574751, 2025). "Chimpanzee SLC52A2-, human SLC52A2-, chimpanzee SLC52A1-, and human SLC52A1-expressing MDTF cells, designated MDTF-chSLC52A2, MDTF-huSLC52A2, MDTF-chSLC52A1, and MDTF-huSLC52A1, respectively, were characterized by permissiveness to CERV-1 Env-pseudotyped virus infection, whereas MDTF cells were not." (PMID 40574751, 2025).
ariboflavinosis (1 paper, 2025). A dietary deficiency of riboflavin causing a syndrome chiefly marked by cheilitis, angular stomatitis, glossitis associated with a purplish red or magenta-colored tongue that may show fissures, corneal vascularization, dyssebacia, and anemia. "Ariboflavinosis resulting from mutations in SLC52A2 can be treated with high oral doses of RF supplementation that improve neurodegenerative symptoms." (PMID 40684659, 2025).
Childhood onset (1 paper, 2020). Onset of disease at the age of between 1 and 5 years. "This is a rare, childhood-onset disease characterized by motoneuron degeneration and caused by mutations in SLC52A2 and SLC52A3, encoding riboflavin (RF) transporters (RFVT2 and RFVT3, respectively), resulting in muscle weakness, ponto-bulbar paralysis and sensorineural deafness." (PMID 33036493, 2020).
cranial neuropathies (1 paper, 2014). "We used both exome and Sanger sequencing to identify SLC52A2 mutations in patients presenting with cranial neuropathies and sensorimotor neuropathy with or without respiratory insufficiency." (PMID 24253200, 2014).
hepatocellular carcinoma (1 paper, 2022). A malignant tumor that arises from hepatocytes. "In conclusion, we have systematically described for the first time that SLC52A2 is closely associated with a variety of tumors, especially hepatocellular carcinoma." (PMID 34991609, 2022). "The SNHG3 and THUMPD3-AS1/hsa-miR-139-5p-SLC52A2 axis were identified as potential regulatory pathways in hepatocellular carcinoma." (PMID 34991609, 2022). "In hepatocellular carcinoma, the SLC52A2 expression is an independent prognostic factor." (PMID 34991609, 2022).
meningioma (1 paper, 2022). A generally slow growing tumor attached to the dura mater. "Specifically, the meningioma cell lines and colorectal cell lines express the highest levels of SLC52A2." (PMID 34991609, 2022).
Nystagmus (1 paper, 2022). Rhythmic, involuntary oscillations of one or both eyes related to abnormality in fixation, conjugate gaze, or vestibular mechanisms. "SLC52A2 missense mutations located in the C-terminal regions tend to result in an early age of onset, with nystagmus as the first symptom." (PMID 36186484, 2022).
sensory ataxia (1 paper, 2014). Any ataxia in which the causes of the disease is a perturbation of the sensory system, leading to its dysfunction. "This is in stark contrast with our cohort of patients with mutations in SLC52A2 who presented with sensory ataxia and nerve conduction studies revealing an axonal sensorimotor neuropathy." (PMID 24253200, 2014).
Sensory neuropathy (1 paper, 2014). Peripheral neuropathy affecting the sensory nerves. "In contrast, the most common presenting symptom in our cohort of patients with SLC52A2 mutations is an ataxic gait, which in young children is likely the first indication of an underlying sensory neuropathy." (PMID 24253200, 2014).
neurological disorder (6 papers, 2017 to 2025). "Our findings draw important parallels with RF transporter deficiency disease (RTD), a neurological disorder caused by mutations in SLC52A2 (RTD2) or SLC52A3 (RTD3) that manifests in infancy." (PMID 40684659, 2025). "Mutations in the SLC52A2 gene, which encodes the riboflavin transporter RFVT2 and is responsible for Brown–Vialetto–Van Laere syndrome, decrease riboflavin absorption and have been related with neurological disorders in early stages of development." (PMID 39063339, 2024).
infection (5 papers, 2007 to 2025). The state of being infected such as from the introduction of a foreign agent such as serum, vaccine, antigenic substance or organism. "The infection with a pseudo-virus showed that MDTF cells expressing human SLC52A2 and chimpanzee SLC52A1 had a higher infection titre." (PMID 40574751, 2025). "The ectopic expression of human and chimpanzee SLC52A2 and its related SLC52A1 in heterogenic cells confers susceptibility to infection by CERV1 and porcine endogenous retrovirus (PERV)." (PMID 40574751, 2025). "On the other hand, it is unknown whether a serine at position 109 of SLC52A2 affects CERV1 infection." (PMID 40574751, 2025). "Notably, CERV1 infection is observed in human cell lines that express human SLC52A2 abundantly but hardly express human SLC52A1." (PMID 40574751, 2025). "Since it was confirmed that NCMDF cells have a serine at position 109 of SLC52A2, it is thought that SLC52A1 functions as the entry receptor for PERV-A/C infection in NCMDF cells." (PMID 40574751, 2025).
cancer (3 papers, 2022 to 2025). A tumor composed of atypical neoplastic, often pleomorphic cells that invade other tissues. "We estimated the association between the SLC52A2 expression and the clinical features across human cancers using TCGA data." (PMID 34991609, 2022). "We further analyzed the mutation distribution of the SLC52A2 gene in multiple human cancers by the COSMIC database." (PMID 34991609, 2022). "Although the expression of hsa-miR-122-5p was also lower in cancer, and prognostic analysis found that its high expression was associated with poor prognosis, which contradicted the relationship between SLC52A2 and prognosis." (PMID 34991609, 2022). "Interestingly, we also revealed that patients with cancer harboring SLC52A2 mutations had a worse prognosis." (PMID 34991609, 2022). "Finally, we also explored the diagnostic value of SLC52A2 expression in pan-cancer." (PMID 34991609, 2022). "Nevertheless, the detrimental role of riboflavin and its associated transporters, namely SLC52A2 and SLC52A3, in cancer has been extensively characterized." (PMID 38430255, 2024). "As for TMB, our results also demonstrated that the SLC52A2 expression was significantly related to TMB in 13 human cancers." (PMID 34991609, 2022). "Subsequently, the CCLE database was used to estimate the SLC52A2 expression in various cancer cell lines." (PMID 34991609, 2022). "In summary, we found that SLC52A2 is closely related to the formation of the cancer-promoting immune microenvironment." (PMID 34991609, 2022). "Next, we analyzed the difference in mRNA expression of SLC52A2 between various cancer and normal tissues using the ONCOMINE database." (PMID 34991609, 2022). "Our results show that SLC52A2 positively correlates with the expression of multiple immune checkpoint genes in pan-cancer, which is consistent with the conclusion that high SLC52A2 expression is related to a poor prognosis." (PMID 34991609, 2022). "TCGA database was used to estimate the correlation between SLC52A2 expression and survival in multiple human cancers." (PMID 34991609, 2022). "To further estimate SLC52A2 expression in multiple human cancers, we examined mRNA sequencing data from the TCGA database." (PMID 34991609, 2022). "Besides, we estimated the correlation between genetic alteration of SLC52A2 and the prognosis of cancers by the cBioPortal database." (PMID 34991609, 2022). "We analyzed the alteration frequency of SLC52A2 in pan-cancer by the cBioPortal database." (PMID 34991609, 2022). "We found that the SLC52A2 expression was more elevated in all cancers." (PMID 34991609, 2022). "Therefore, we estimated the relationship between the MSI, TMB, and SLC52A2 expression in pan-cancer." (PMID 34991609, 2022). "In this study, bioinformatic analysis was conducted to explore the SLC52A2 expression in various human tumors and its possible association with cancer, which was confirmed by immunohistochemistry, to provide more information to better understand the importance of SLC52A2 in various cancers." (PMID 34991609, 2022). "In conclusion, our study demonstrated that SLC52A2 was highly expressed in almost all tumors and associated with poor prognosis, diagnosis, mutations, TMB, MSI, common immune checkpoint genes, and immune cells infiltration in most cancers." (PMID 34991609, 2022). "Thus, SLC52A2 may play a crucial role in immune escape and macrophage M2 polarization in the cancers microenvironment." (PMID 34991609, 2022). "As a result, 285 SLC52A2+NOTCH1+ cells were clustered from CNV+ cancer cells in GSE131907, representing 65.2% of all the SLC52A2+NOTCH1+ cells selected by Seurat’s WhichCells module." (PMID 41453945, 2025). "To explore whether the currently published articles on SLC52A2 expression and cancer are consistent with our conclusions, we searched PubMed, Embase, the Cochrane Library, on April 30, 2021, using the following terms in [All Fields]: BVVLS2, GPR172A, SLC52A2, HRFT3, GPCR41, RFVT2, RFT3, BVVLS2." (PMID 34991609, 2022).
tumor (2 papers, 2019 to 2022). "SLC52A2 expression was linked to patient overall survival, disease-specific survival, progression-free interval, diagnosis, mutations, tumor mutational burden, microsatellite instability, common immune checkpoint genes, and immune cells infiltration." (PMID 34991609, 2022). "In this study, we systematically analyzed the association of SLC52A2 with multiple human tumor types." (PMID 34991609, 2022). "Our study showed that the expression of SLC52A2 was positively associated with TBM and MSI in most tumor types." (PMID 34991609, 2022). "We also validated the relationship between SLC52A2 and the prognosis of LIHC patients using the GSE14520 dataset, which showed that high SLC52A2 expression in tumor tissues correlated with poor prognosis of patients." (PMID 34991609, 2022). "The results demonstrated that the SLC52A2 was expressed in all 38 kinds of tumor cell lines." (PMID 34991609, 2022). "We found that of the 28 tumors whose normal tissues could acquire through the ONCOMINE, GTEx, and TCGA databases, 27 of them were highly expressed, and SLC52A2 expression increased with increasing tumor stage in multiple tumors." (PMID 34991609, 2022). "They found that SLC52A2 expression was increased in tumor tissues (P < 0.001)." (PMID 34991609, 2022). "Finally, we analyzed the correlation between SLC52A2 expression and tumor status." (PMID 34991609, 2022). "Thus, we hypothesize that the rapid metabolism and proliferation of tumor cells increases the rate of riboflavin consumption and uptake, which in turn induces the SLC52A2 expression in the organism to facilitate the supply of cytosolic riboflavin." (PMID 34991609, 2022). "Therefore, tumor patients with high SLC52A2 expression may have a higher response rate to ICIs." (PMID 34991609, 2022). "Chi-squared analysis revealed that male patients (P = 0.034) and patients with larger tumor size (P = 0.043), poor tumor differentiation (P = 0.025), TNM stage III–IV (P = 0.157), vascular invasion (P = 0.236) appeared to exhibit the higher expression of SLC52A2." (PMID 34991609, 2022). "We further explored the relationship of SLC52A2 with different functional immune infiltrating cells, including T cell (general, CD8+, Th1, Th2, Tfh, Th17, Treg, and T cell exhaustion), B cell, monocyte, tumor-assisting macrophages (TAMs), M1 and M2 macrophage, neutrophil, and Dendritic cell." (PMID 34991609, 2022).
neurodegenerative disease (1 paper, 2022). A disorder of the central nervous system characterized by gradual and progressive loss of neural tissue and neurologic function. "This childhood-onset neurodegenerative disease is caused by biallelic pathogenic variants in either SLC52A2 or SLC52A3 genes, resulting in insufficient supply of riboflavin (vitamin B2) and consequent impairment of flavoprotein-dependent metabolic pathways." (PMID 35740351, 2022).
SLC52A2 also shares sentences with these, for which no sentence is quoted: breast carcinoma (2 papers); hearing loss (2); neuropathies (2); rectal cancer (2); absence seizures (1); asthma (1); breast tumor (1); Charcot-Marie-Tooth disease type (1); colon cancer (1); colorectal cancer (1); diabetes (1); distal hereditary motor neuropathies (1); eczema (1); Encephalopathy (1); Epileptic encephalopathy (1); esophageal squamous cell carcinoma (1); Friedreich ataxia (1); GM1 gangliosidosis (1); hay fever (1); hereditary spastic paraplegia 7 (1); melanoma (1); peripheral T cell lymphoma (1); polyneuropathy (1); Respiratory insufficiency (1); retinitis pigmentosa (1); Sensorimotor neuropathy (1); spinal muscular atrophy (1); Wilson disease (1).